BRAF (B-Raf proto-oncogene, serine/threonine kinase)
Diseases named in the same sentence as BRAF in open-access papers (continued):
Sharing a sentence is not in itself a finding about the gene and the disease.
melanoma (continued). "For example, in a recent genome-wide screen testing resistance to BRAF inhibitors in melanoma cells, CRISPR/Cas9-mediated activation of more than 10,000 lncRNAs revealed 16 candidate loci conferring resistance to BRAF inhibition." (PMID 31690629, 2020). "Vorinostat enhances the efficacy of BRAF/MEK inhibitors in N-RAS and NF-1 mutant melanomas by suppressing DNA repair pathways." (PMID 32626712, 2020). "As a result, combination therapy with BRAF and MEK inhibitors, including trametinib and cobimetinib, has become standard due to multi-pronged blockade of melanoma growth pathways." (PMID 32429485, 2020). "Accordingly, BRAF- and MEK- inhibitors gained increasing interest as therapeutic options for melanoma, in many cases in combinatorial therapy." (PMID 32630674, 2020). "Melanoma spheroids, which survived MEK inhibitors or BRAF inhibitors, recovered and expanded after cessation of treatment, as demonstrated by FUCCI imaging." (PMID 32957652, 2020). "Yet, in the setting of melanoma or other tumors, there can be no doubt regarding the oncogenic role of BRAF V600E mutations, based on preclinical modeling and also on the tumor regression that results from the use of antagonists such as BRAF and MEK inhibitors." (PMID 32066498, 2020). "By analyzing an accessible small series of paired melanoma samples, we found that a relatively poorly studied NRP1-ligand, Galectin-1, is induced upon the onset of resistance to BRAF inhibitors." (PMID 32784465, 2020). "New therapeutic concepts such as anti-PD-1-based immunotherapy or targeted therapy with BRAF and MEK inhibitors have significantly improved the survival of melanoma patients." (PMID 33260923, 2020). "In melanoma, paradoxical activation of the MAPK pathway induced by BRAF inhibitors in macrophages results in upregulation and secretion of the vascular endothelial growth factor, which in turn restores MAPK signaling and promotes resistance in tumor cells." (PMID 33291749, 2020). "RAF1 fusion was detected in 4 cases (GC, melanoma, STS, and pancreatic cancer), BRAF fusion in 2 cases (BTC and STS), ALK fusion in 2 cases (CRC and BTC), ROS1 fusion in 1 case (CRC), and EGFR fusion in 1 case (CRC) with diverse counterparts." (PMID 32411236, 2020). "Primary resistance to BRAF is induced due to HGF secretion by stroma cells (i.e., fibroblasts) within the tumor and its paracrine signaling to melanoma cells." (PMID 32605090, 2020). "In melanoma, YAP overexpression confers resistance to BRAF inhibitor, whereas YAP depletion increases drug sensitivity." (PMID 32749065, 2020). "Dabrafenib (BRAF inhibitor) and trametinib (MEK inhibitor) combination therapy is used currently for melanoma and non–small lung carcinoma treatment and is more efficient than dabrafenib alone in inhibiting the pathway." (PMID 33268358, 2020). "The combined therapy of BRAF and MEK inhibitors has been proved to improve the rate of progression-free survival in melanoma patients compared with BRAFi alone." (PMID 32532957, 2020). "In addition to the incomplete reagent toolbox, while some tumor histology's are genetically and phenotypically very similar between canines and humans (e.g., osteosarcoma) others have specific differences such as the near absence of BRAF mutations in canine melanoma." (PMID 32117739, 2020). "Although it is not clear how the JNK and mTORC1 pathways cross-talk, these findings were confirmed and also shown to mediate resistance to joint BRAF and MEK inhibition in melanoma." (PMID 32046099, 2020). "In the last decade, multiple large-scale sequencing studies have elucidated the genetic landscape of cutaneous melanoma and led to the classification of the genetic subtypes BRAF mutant, RAS mutant, NF1 mutant or triple wild-type melanoma." (PMID 32825510, 2020). "Increased expression of this lectin was also observed in the plasma of BRAF/MEK inhibitor‐treated, progressing melanoma patients." (PMID 32330348, 2020).
melanoma (continued). "Recently, HDAC inhibitors were shown to dramatically enhance the efficacy of BRAF/MEK inhibitors in sensitive and insensitive RAS pathway–driven melanomas." (PMID 32266211, 2020). "Melanoma cells fast respond to this new microenvironment by increasing ECM attachment, and reactivating MAPK signaling in a BRAF‐independent manner." (PMID 32749065, 2020). "To identify other potential therapeutic targets, we analyzed the TCGA data for differences in gene and/or protein expression between BRAF-MUT and BRAF-WT melanoma." (PMID 32764384, 2020). "Most relevant molecular drivers that participate to melanoma metabolic plasticity include AKT, BRAF, p14ARF, MYC, NRAS, phosphatidylinositol-4,5-bisphosphate 3 kinase catalytic subunit α (PIK3CA) and phosphatase and tensin homolog (PTEN)." (PMID 32528879, 2020). "Thus, TD prior to BRAF/MEK-inhibitor application might be effective in melanoma treatment." (PMID 32626653, 2020). "Nelfinavir has been identified as a potent suppressor of PAX3 and MITF expression and sensitizer of BRAF and NRAS mutant melanoma cells to MAPK pathway inhibitors." (PMID 33322354, 2020). "While both BRAF/MEKi3, 8, 9 and aPD‐110, 12 have the US Food and Drug Administration (FDA) approval for patients with advanced BRAF‐mutant melanoma, limited evidence exists comparing those treatment options." (PMID 32871054, 2020). "Ganetespib induced tumor regression in melanoma xenografts when supplied together with the MEK inhibitor TAK-733 and with the BRAF(V600E) inhibitor vemurafenib." (PMID 32766157, 2020). "Retrospective studies of spitzoid neoplasms have found activating fusions involving BRAF, RET, ROS1, ALK, or NTRK1 in 39% of melanomas with spitzoid morphology and just over 50% of Spitz nevi and atypical Spitz tumors." (PMID 32123303, 2020). "DAB activity was proven by the decreased ERK phosphorylation in primary melanoma cells (SKmel28 BRAFV600E cell line), while TSA effect was evidenced by acetylated histones accumulation in cell's nuclei (SKmel23 BRAF WT cell line)." (PMID 32266211, 2020). "We focused our attention on EGFR, BRAF, KRAS, and BRAF genes for NSCLC, melanoma, and mCRC samples, respectively." (PMID 32054005, 2020). "The inhibition of BRAF and MEK leads to up-regulation of melanoma differentiation antigens (MDA), such as MART-1, gp-100 and tyrosinase, and MHC expression along with decreased immunosuppressive cytokines secretion." (PMID 32054102, 2020). "While presently far behind BRAF and MEK inhibitors in development, there has been a recent increase in the development and evaluation of ERK inhibitors for treating BRAFV600E melanoma." (PMID 32092958, 2020). "Following our finding that BCL2L10 is implicated in melanoma resistance to cisplatin and ABT-737, we wanted to evaluate whether the effect of BCL2L10 expression in response to these drugs was also observed in the context of simultaneous inhibition of BRAF by the BRAFV600E inhibitor PLX-4032." (PMID 33396645, 2020). "They found that miR-200c reverts drug resistance to PLX4720 BRAF and U0126 MEK inhibitors by down-regulating the p16 transcriptional repressor BMI-1, which, in turn, inhibits melanoma cell growth and metastases in nude mice." (PMID 32604720, 2020). "Nevertheless, a study published in 2019 focusing on BRAF and MEK inhibitors has evaluated the miRNA profiling of melanoma patients at baseline and during resistance acquirement to therapy." (PMID 32185171, 2020). "We are aware that our data do not directly allow to correlate SPV122 effects as potentiator of BRAF and MEK inhibitors in melanoma, with inhibition of retrotransposon activity." (PMID 32933538, 2020). "This meta-analysis suggested that combined BRAF-MEK targeted therapy is optimal for BRAF-mutant patients and can enhance the favorable outcomes in advanced melanoma." (PMID 33256107, 2020).
melanoma (continued). "Targeted therapies, however, can be very effective against established BM from different entities, such as BRAF and MEK inhibitors in melanoma, EGFR and ALK inhibitors in lung adenocarcinoma, and immune checkpoint inhibitors in melanoma and lung cancer." (PMID 32918638, 2020). "Integrin α5β1 promotes in melanoma cells the FAK-mediated ERK reactivation and resistance to BRAF inhibitors." (PMID 33036192, 2020). "Importantly, TM also suppressed S6 phosphorylation in non-BRAF mutated melanoma cell lines indicating a broader therapeutic potential of TM in patients without the BRAF mutation but where the PI3K/Akt/mTOR pathway is activated such as in patients harboring NRAS mutations." (PMID 32085796, 2020). "SREBP-1 contributes to the anti-tumor response induced by BRAF inhibition, and SREBP-1 inhibition sensitizes therapy-resistant melanoma cells to MAPK-targeting therapy." (PMID 31910904, 2020). "Current preclinical and clinical trials are underway to determine the efficacy and benefits of combining immunotherapy treatment regimen alone or in combination with BRAF and MEK inhibitors for treatment of patients with BRAF mutant melanoma." (PMID 32092958, 2020). "All our tested melanoma cell lines both BRAFV600E and BRAF WT were sensitive to AKT, PI3K and pan-mTOR inhibition with IC50 values in a similar range as that of TM." (PMID 32085796, 2020). "Recently therapy that targets the MAPK signaling (BRAF/MEK inhibitors) and immunotherapy (anti-CTLA4 and anti-PD1 agents) have changed the therapeutic approaches to stage IV melanoma." (PMID 32575838, 2020). "Another explanation was that acral melanoma was reported to have a significantly lower proportion of BRAF mutations than non-acral cutaneous melanoma, and BRAF mutation in melanoma was associated with poor prognosis, which may lead to a better prognosis for acral melanoma in this study." (PMID 31901239, 2020). "Vemurafenib (selective BRAF inhibitors) and trametinib (Inhibitors of the downstream MAP kinase MEK) were targeted inhibitors utilized for the treatment of melanoma." (PMID 32129945, 2020). "However, our study showed that combining anti-PD1 with BRAFi and/or MEKi might be an interesting rescue line, especially in patients with advanced BRAF WT melanomas for whom therapeutic options are limited, with tumor control achieved in more than half of patients and relatively good tolerance." (PMID 32585901, 2020). "The authors show phendione induces DNA damage response without causing DNA breaks or inducing cellular dormancy, therefore blocking tumor growth of BRAF mutant and NRAS mutant melanomas." (PMID 32241802, 2020). "Here the authors report a phase 1 clinical trial testing the anti-PD-L1 antibody durvalumab in combination with the BRAF inhibitor dafrafenib and the MEK inhibitor trametinib in patients with BRAFV600-mutant melanoma." (PMID 33288749, 2020). "Co-targeting melanoma with BRAF/MEK and PI3-K inhibitors to overcome BRAF inhibitor- resistance provided further evidence showing that a combination targeted therapy is necessary for melanoma treatment 18-20." (PMID 32863956, 2020). "They selectively target BRAF kinase and thus interfere with the MAPK signalling pathway that regulates the proliferation and survival of melanoma cells." (PMID 32645969, 2020). "Resistance to BRAFV600E in BRAF monotherapy was overcome by combining BRAF and MEK inhibition in melanoma." (PMID 32337094, 2020). "Of the seven patients participated in the crossover, five received BRAF-targeted therapy and five received CPI at the time of melanoma progression." (PMID 32467299, 2020). "Before the introduction of ICIs and anti-BRAF/MEK agents, chemotherapy was the standard of care for melanoma patients." (PMID 32708968, 2020). "We assessed inhibition activity on BRAF and ERK signaling in melanoma cells expressing BRAFV600E monomers (A375 cells) and constitutively expressed p61BRAFV600E dimers (SKMEL239-C4 cells)." (PMID 32873792, 2020).
melanoma (continued). "By inhibiting BRAF they interfere with the MAPK signalling pathway that regulates the proliferation and survival of melanoma cells." (PMID 32645969, 2020). "One of the best-studied examples of the dynamic effects of targeted therapy on the microenvironment is with the use of BRAF and MEK inhibitors for melanoma." (PMID 32467593, 2020). "Combinations of BRAF inhibitors and MEK inhibitors (BRAFi + MEKi) are Food and Drug Administration (FDA)-approved to treat BRAF V600E/K mutant melanoma." (PMID 32093389, 2020). "Recently, we identified wildtype KRAS as a novel therapeutic target in melanoma and showed that KRAS inhibition functions synergistically with BRAF inhibition." (PMID 31906510, 2020). "BRAF inhibitors vemurafenib (PLX4032) and dabrafenib improve survival of BRAF-mutant melanoma patients compared to chemotherapy, which lead to FDA approval for this treatment in BRAF-mutant melanoma." (PMID 32413516, 2020). "This ADC along with BRAF and MEK inhibitors has shown efficacy in treatment naïve and MAPK pathway inhibitor resistant melanoma." (PMID 32092958, 2020). "Attempts at monotherapy BRAF inhibition as well as combination BRAF and MEK inhibition, as used in melanoma, have been unsuccessful due to EGFR-mediated adaptive feedback." (PMID 32384640, 2020). "We selected four melanoma cell lines for analysis: SKMEL5 and SKMEL28 (BRAF mutant), and SKMEL2 and IPC298 (NRAS mutant)." (PMID 32488085, 2020). "BRAF-mutant tumours with constitutive upregulation of the MAPK pathway, such as melanoma, can induce immune-escape mechanisms that make them immunologically “cold” and able to evade T-cell immune responses." (PMID 32645969, 2020). "Recently, additional new combinations of BRAF and MEK inhibitors were approved for their usage in malignant melanoma, such as the BRAF inhibitor, encorafenib, and MEK inhibitors, cobimetinib, and binimetinib." (PMID 33256089, 2020). "The aim of our study is to investigate the role of EVs in the mechanisms of drug resistance and phenotypic alteration in primary melanoma cell lines MEL50 BRAF-V600mut and M257 BRAF-Wild Type." (PMID 32046729, 2020). "miR-146a-5p expression was inversely correlated with drug sensitivity and COX2 expression and was reduced in BRAF and MEK inhibitor-resistant melanoma cells and tissues." (PMID 32967672, 2020). "To further verify and characterize cell death observed following treatment of melanoma cells with TM, we assessed apoptosis using TUNEL staining in representative BRAFV600E and BRAF WT melanoma cell lines, RPMI and B16F10 cell lines respectively." (PMID 32085796, 2020). "Thanks to these basic researches, the emergence and approval of inhibitors like BRAF, RAS and MEK bring a promising treatment for melanoma patients." (PMID 33136551, 2020). "Therapeutic blockade of calcineurin/NFAT pathways not only induced apoptosis of melanoma cells, it also enhanced the antitumor effects of target-specific drugs, such as MEK or BRAF inhibitors." (PMID 33091721, 2020). "Vemurafenib, BRAF inhibitor (BRAFi), approved by the Food and Drug Administration (FDA) in 2011, demostrated a low toxicity level and high efficiency in melanoma patients." (PMID 33091721, 2020). "In one study seeking therapeutically targetable gene fusions in multiple cancer types, FISH for BRAF and RAF1 performed on 131 melanomas identified one BRAF rearrangement and one RAF1 rearrangement." (PMID 32123303, 2020). "Additionally, the mutational status of melanoma patients bearing BM did not apparently influence OS, although a positive trend was seen in BRAF-mutated patients treated with immunotherapy (14.2 months) as compared to those treated with targeted therapy alone (8.8 months)." (PMID 33042809, 2020). "For this purpose, melanoma cell lines with mutant BRAF, NRAS, or cKIT and with acquired resistances to BRAF, MEK, or cKIT inhibitors, respectively, were investigated using both 1H-NMR-based metabonomic and protein microarrays." (PMID 32455924, 2020).
melanoma (continued). "Upregulation of IGF-IR is detected in melanoma that acquires resistance to the Erk1/2 inhibitor SCH772984, the BRAF inhibitor vemurafenib, and the MEK inhibitor trametinib." (PMID 32493414, 2020). "Indeed, both silencing of the activated SHP-2 E76K mutant or the administration of the allosteric SHP-2 inhibitor, SHP099, causes regression of the established melanoma, thereby suggesting that SHP-2 could be considered as a therapeutic target for BRAF wild-type melanoma." (PMID 33003469, 2020). "Cardiovascular adverse events (CVAEs) after treatment with BRAF and MEK inhibitors in patients with melanoma remain incompletely characterized." (PMID 31397860, 2019). "The serine threonine kinases BRAF and MEK are major regulators of the ERK/MAP kinase pathway, which is deregulated in the majority of melanomas." (PMID 30277012, 2019). "Our further observations support the experience that BRAF and NRAS mutant melanomas behave differently during metastatic progression." (PMID 31391014, 2019). "The selective FDA-approved BRAF inhibitor vemurafenib (PLX4032), achieves an impressive clinical response in melanoma, but fails in most CRCs." (PMID 31861874, 2019). "Regarding the fact that many melanoma patients carry a BRAF mutation, and that they develop resistance to BRAF inhibitors, this observation is very interesting as MIF inhibitors could be used to treat many patients in relapse after treatment with an inhibitor of the mutant BRAF protein." (PMID 31013837, 2019). "In this respect, the most common somatic mutations of Kirsten Rat Sarcoma Viral Oncogene Homolog KRAS and BRAF oncogenes are known to play an important role in the advance and progression of both colorectal cancer (CRC) and melanoma." (PMID 30935124, 2019). "This discovery led to the development of mutant-specific inhibitors of BRAF, vemurafenib (PLX4032) and dabrafenib, which provided better clinical responses, including improved overall survival of melanoma patients compared with standard chemotherapy regimens." (PMID 31091806, 2019). "The BRAF and MEK small molecule inhibitors induce dramatic responses of BRAF-mutant melanomas that often endure only months." (PMID 31014399, 2019). "Small-molecule inhibitors of BRAF and its downstream-target MEK have already been approved for other BRAF-driven cancer types, such as melanoma and have been shown to effectively inhibit glioma growth both in preclinical models and small patient cohorts." (PMID 31391125, 2019). "One of the best preserved exclusionary relationships is that between BRAF(V600E) and NRAS(Q61) in melanomas." (PMID 30651601, 2019). "To assess the role of ITCH in TNFα-triggered BRAF activation, we found that p-MEK and p-ERK were refractory to TNFα treatment in ITCH-depleted melanoma cells." (PMID 31015455, 2019). "The B-raf/MEK pathway is a driver of cancer cell proliferation and survival in BRAF-mutant melanoma; inhibition of this pathway with vemurafenib results in programmed cell death in these melanoma cells." (PMID 31508362, 2019). "Additionally, the expression of MDAs could be increased in any melanoma cells regardless of BRAF mutation status." (PMID 31134073, 2019). "These deregulations reflect the crucial role of BRAF and the MAPK pathway in governing melanoma cell survival and proliferation." (PMID 30277012, 2019). "Targeted therapy was initiated as the melanoma was BRAFV600E positive; however, new tumours were identified on the back region during BRAF inhibition." (PMID 30900145, 2019). "BRAF V600E, p-ERK and ERK was respectively detected by Western blot assay in melanoma cells (A375, SK-mel-28, G361 and A431)." (PMID 30717768, 2019). "In contrast, Akt pathway activation by SC79 increased H3K4me3 and the combination of SC79 and magnolol increased H3K4me3 in both BRAF‐ and NRAS‐mutant melanoma cells (Supplem)." (PMID 30793515, 2019).